RBM15 (RNA binding motif protein 15)
Diseases named in the same sentence as RBM15 in open-access papers (continued):
Sharing a sentence is not in itself a finding about the gene and the disease.
osteosarcoma (13 papers, 2021 to 2025). A usually aggressive malignant bone-forming mesenchymal neoplasm, predominantly affecting adolescents and young adults. "In osteosarcoma, RBM15 has been implicated in circRNA-mediated m6A regulation of tumor metabolism and progression." (PMID 41403702, 2025). "RBM15 could be possible m6A-related biomarker for predicting the prognosis of osteosarcoma with much lower survival rates in the high-risk group than in the low-risk group." (PMID 37002245, 2023). "Our study showed that γδ T cells in osteosarcoma are closely associated with RBM15." (PMID 37002245, 2023). "RBM15 suppressed the ferroptosis and promoted proliferation and metastasis in osteosarcoma cells by mediating the m6A modification of MAT2A." (PMID 40682199, 2025). "This study highlights the critical role of the circ-CTNNB1/RBM15/m6A axis in metabolic reprogramming and osteosarcoma progression, offering a potential therapeutic target." (PMID 41403702, 2025). "In osteosarcoma cells, RBM15 exhibits elevated expression levels, a phenomenon notably linked to an unfavorable prognosis." (PMID 38915367, 2024). "For instance, Circ‐CTNNB1 promotes m6A modification by interacting with RBM15 in osteosarcoma cells to drive glucose metabolism reprogramming." (PMID 39661501, 2024). "In the field of cancer research, RBM15 has also been shown to impact the progression of various cancers, including squamous cell carcinoma 41, osteosarcoma 42, ovarian cancer 43 and lung cancer 44, by interacting with different proteins." (PMID 39113895, 2024). "After performing statistical analysis, the rate of positive specific staining for RBM15 was higher in osteosarcoma than in paraneoplastic tissues, and the difference was statistically significant (P < 0.05)." (PMID 37002245, 2023). "This would suggest that when the RBM15 gene is overexpressed, T cells gamma delta expression is reduced in osteosarcoma." (PMID 37002245, 2023). "The results demonstrated that the positive area of specific staining expression of RBM15 was significantly more abundant in osteosarcoma than in paraneoplastic tissues (Fig. 11A1–B2)." (PMID 37002245, 2023). "This suggests that when RBM15 gene expression is high, the expression of natural killer (NK) cells in osteosarcoma is also correspondingly increased." (PMID 37002245, 2023). "In other words, if an increased RBM15 is detected in a patient with osteosarcoma, then this patient is insensitive to Denileukin Diftitox Ontak." (PMID 37002245, 2023). "The results of qRT-PCR experiments showed that the expression of RBM15 was significantly higher in both osteosarcomas than in the control cell lines." (PMID 37002245, 2023). "Subsequently, we examined the RBM15 gene by qRT-PCR using in vitro cellular assays and found that its expression was indeed higher in the osteosarcoma cell line than in the control cell line, which further confirmed the accuracy of our analysis." (PMID 37002245, 2023). "This is consistent with the results of this study, which showed a significant positive correlation between RBM15 and NK cell activation in osteosarcoma." (PMID 37002245, 2023). "After cell culture, RNA extraction, primer design and QRT-PCR laboratory manipulation, we obtained the expression of RBM15 in osteosarcoma cells as well as in control cells." (PMID 37002245, 2023). "Mechanistic studies on how RBM15 regulates osteosarcoma are scarce, but a recent study suggested that RBM15 directly interacts with Circ-CTNNB1, thereby increasing the level of m6A modification of genes associated with aerobic glycolysis, and ultimately facilitating the glycolytic process." (PMID 38915367, 2024). "Finally, we found that the expression of RBM15 in both osteosarcoma cell lines was much higher than that in the control cell lines by qRT-PCR in vitro, and the difference was statistically significant (P < 0.05)." (PMID 37002245, 2023). "RBM15 and YTHDC1 can serve as potential prognostic biomarkers associated with m6A in osteosarcoma." (PMID 37002245, 2023).
osteosarcoma (continued). "Several m6A genes, including METTL3, RBM15, IGF2BP3, and RNA-binding motif protein X (RBMX), were significantly upregulated in OS cell lines and OS tissues compared to osteoblast and non-osteosarcoma tissues." (PMID 40510136, 2025). "Based on two large-scale cohorts, HNRNPA2B1, HNRNPC, RBM15, YTHDF1, and YTHDC1 expression levels are upregulated in osteosarcoma tissues." (PMID 34094986, 2021). "Additionally, prior research has demonstrated that the interaction between RBM15 and circ‐CTNNB1 in osteosarcoma stimulates the growth of the tumour by promoting the expression of HK2." (PMID 39661501, 2024). "In addition, RBM15 interacts with circ-CTNNB1 to enhance the expression of HK2, GPI and PGK1 in an m6A modification-dependent manner, leading to the promotion of the glycolytic process and the development of osteosarcoma." (PMID 37474926, 2023).
gastric cancer (12 papers, 2019 to 2026). A primary or metastatic malignant neoplasm involving the stomach. "In gastric cancer, RBM15 expression is significantly elevated and associated with poor prognosis." (PMID 41403702, 2025). "In gastric cancer 15, using 3 m6A RNA methylation regulators (FTO, RBM15, ALKBH5), a prognostic risk signature was established." (PMID 33033522, 2020). "RBM15 as a “writer” has been found to be differentially expressed in the head and neck squamous cell carcinoma, gastric cancer and colorectal adenocarcinoma." (PMID 32974160, 2020). "RBM15 can also function as an independent prognostic marker and a predictor for clinical pathological features of gastric cancer." (PMID 32974160, 2020). "In contrast, high expression of ALKBH5 (HR = 0.94, 95% CI = 0.89–0.98) and RBM15 (HR = 0.83, 95% CI = 0.74–0.93), have a better survival in patients with gastric cancer." (PMID 31681576, 2019). "In gastric cancer, a risk signature was constructed using 3 m6A RNA methylation regulators (FTO, RBM15, and ALKBH5), which not only was an independent prognostic marker but could also predict the clinicopathological features of gastric cancer." (PMID 33628782, 2021). "Moreover, compare with low risk group patients, gastric cancer patients generally contain a higher proportion of FTO, lower proportion of ALKBH5 and RBM15 in the high risk group." (PMID 31681576, 2019). "The results showed that RBM15 (HR = 0.69, 95% CI = 0.52–0.92), FTO (HR = 1.46, 95% CI = 1.09–1.96), MSI2 (HR = 0.75, 95% CI = 0.58–0.97) and ZC3H7B (HR = 0.70, 95% CI = 0.53–0.93) was associated with prognosis in gastric cancer patients and the RiskSscore model was established." (PMID 36003776, 2022). "Four genes, RBM15, FTO, MSI2 and ZC3H7B were identified as influencing the prognosis of gastric cancer patients in univariate analysis of 24 regulators." (PMID 36003776, 2022). "The detection of mRNA levels of m6A-modified enzymes (METTL3, WTAP, METTL14, VIRMA, RBM15, FTO, and ALKBH5) in gastric cancer tissues and adjacent tissues showed that the mRNA level of METTL3 was significantly higher in gastric cancer tissues." (PMID 34394353, 2021). "Based on this finding, we derived a risk signature, using 3 m6A RNA methylation regulators (FTO, RBM15, ALKBH5), that is not only an independent prognostic marker but can also predict the clinicopathological features of gastric cancer." (PMID 31681576, 2019).
glioma (12 papers, 2019 to 2025). A benign or malignant brain and spinal cord tumor that arises from glial cells (astrocytes, oligodendrocytes, ependymal cells). "They found that WTAP and RBM15 expression positively correlated with glioma grade and that the high-risk group with high RBM15 expression was more sensitive to TMZ." (PMID 37964279, 2023). "Associations between glioma malignancy grade and the expression of m6 A writers (METTL3, METTL14, WTAP, and RBM15), the reader YTHDF, and erasers (ALKBH5 and FTO) are shown." (PMID 40382536, 2025). "We found that the protein expression of IGF2BP3 and RBM15B was increased in the glioma tissue, while the expression of RBM15 was decreased compared to that in the para-tumor area." (PMID 35559019, 2022). "The expression of WTAP was also significantly correlated with the ‘writers’ of METTL14, KIAA1429 and RBM15 in gliomas." (PMID 30810537, 2019). "Additionally, RBM15 expression has been shown to have prognostic value in glioma, particularly in predicting overall survival in patients with low-grade glioma (LGG)." (PMID 38474421, 2024). "A similar risk signature (ALKBH5, IGF2BP2, IGF2BP3, HNRNPA2B1, YTHDF1, YTHDF2, RBM15, and WTAP) was shown to be prognostic for glioma patients, and the expression of IGF2BP2 and IGF2BP3 was linked to tumour occurrence, development, and progression." (PMID 36831575, 2023). "Other m6A writers in glioma involve KIAA1429, RBM15, and ZC3H13." (PMID 38474421, 2024). "However, WTAP, RBM15, YTHDF, and ALBKH5 had strong correlations with tumor stage and 1p/19q codeletion in glioma." (PMID 33926554, 2021). "As is visible in the violin plot, the mRNA expression levels of YTHDF2, YTHDF1, METTL3, RBM15 and HNRNPC were up‐regulated in glioma compared to normal tissues, whereas the expression levels of ALKBH5, WTAP, YTHDC2, ZC3H13 and METTL14, especially of FTO, were decreased in glioma." (PMID 32449290, 2020). "Moreover, the expressions of WTAP, RBM15, YTHDF2, YTHDF1 and ALKBH5 were highly correlated with each other, and all of their expressions were negatively correlated with FTO in gliomas." (PMID 30810537, 2019).
pancreatic cancer (12 papers, 2020 to 2025). "In pancreatic cancer, RBM15 regulates immune cell infiltration in the TME via m6A modification, particularly influencing macrophage function." (PMID 41403702, 2025). "RBM15 exhibited high expression across various pancreatic cancer cell lines, frequently coexisting with a propensity for T lymphocyte aggregation." (PMID 38915367, 2024). "This also suggests that RBM15 promotes the proliferation, migration, and metastasis of pancreatic cancer cells." (PMID 36831430, 2023). "We carried out further cellular experiments by qPCR, which indicated that the RBM15 gene was highly expressed in pancreatic cancer cell lines (CFPAC-1, BxPC-3), with a significant difference." (PMID 36831430, 2023). "The small interfering RNAs were used to construct pancreatic cancer cell lines with low RBM15 expression." (PMID 36831430, 2023). "We found that in pancreatic cancer patients with a high expression of RBM15, the disease progression was accompanied by a trend of T lymphocyte aggregation." (PMID 36831430, 2023). "We further observed the effect of RBM15 on pancreatic cancer cells by knocking down its expression in pancreatic cancer cell lines." (PMID 36831430, 2023). "Based on bioinformatics technology, we established that RBM15 played a vital role in the progression of pancreatic cancer." (PMID 36831430, 2023). "We found from the immunohistochemical staining of tissue sections from pancreatic cancer patients that those with stronger RBM15 expression show higher levels of lymphocyte counts (p < 0.05)." (PMID 36831430, 2023). "Another study showed that the expression of RBM15 was positively correlated with immune infiltrating cells in pancreatic adenocarcinoma, and RBM15 knockdown suppressed the proliferation of pancreatic cancer cells." (PMID 36864526, 2023). "Next, we knocked down the expression of RBM15 mRNA in pancreatic cancer cell lines SW1990 and PANC-1, which significantly inhibited cell proliferation." (PMID 35223996, 2022). "Cell counting kit-8 (CCK-8) assay showed that knockdown of RBM15 significantly inhibited the proliferation of pancreatic cancer cells." (PMID 35223996, 2022). "The results showed that the protein expression of RBM15 is upregulated in pancreatic cancer, which is similar to the results of the TCGA-GTEx cohort and two GEO datasets." (PMID 33062408, 2020). "This article reports that RBM15 is correlated with pancreatic cancer progression and is an essential prognostic biomarker in pancreatic cancer patients and is correlated with progression by bioinformatic integrated analysis, clinical information statistical analysis and wet experiments." (PMID 36831430, 2023). "In addition, through a series of in vitro and in vivo experiments, we basically determined the oncogenic role of the high expression of RBM15 in pancreatic cancer progression." (PMID 36831430, 2023). "In addition, through a series of in vitro and in vivo experiments, we basically determined the oncogenic role of high expression of RBM15 in pancreatic cancer progression." (PMID 36831430, 2023). "We hypothesize that RBM15 will play an important role in the diagnosis and treatment of pancreatic cancer in the future." (PMID 36831430, 2023). "Moreover, by conducting immunohistochemical experiments, we discovered that RBM15 was considerably more highly expressed in pancreatic cancer tissue than paracancerous normal tissue." (PMID 36831430, 2023). "Intriguingly, elevated blood glucose levels may enhance RBM15 expression in pancreatic cancer." (PMID 38915367, 2024). "Therefore, we hypothesize that RBM15 will play an important role in the diagnosis and treatment of pancreatic cancer in the future." (PMID 36831430, 2023). "Besides, suppression RBM15 could significantly reduce pancreatic cancer cell proliferation in pancreatic adenocarcinoma." (PMID 37732317, 2023).
pancreatic cancer (continued). "By knocking down the expression of RBM15 in the CFPAC-1 and BxPC-3 pancreatic cancer cell lines, we found that these two cell lines inhibit cell proliferation, migration, and metastasis." (PMID 36831430, 2023).
cervical cancer (11 papers, 2022 to 2025). A primary or metastatic malignant neoplasm involving the cervix. "In cervical cancer (CC) tissues, RBM15 is highly expressed, and its elevated levels are associated with malignant tumor characteristics." (PMID 41403702, 2025). "Previous studies have highlighted the oncogenic role of RBM15 in various cancer types, such as breast and cervical cancer." (PMID 40370450, 2025). "For example, RBM15 interacts with the downstream target c-myc, enhancing its m6A modification, a process crucial in cervical cancer development." (PMID 38915367, 2024). "HPV-E6, one of the eight protein-coding genes associated with cervical carcinogenesis, has been shown to maintain high expression of RBM15 in cervical cancer cells by preventing its autophagic degradation." (PMID 38915367, 2024). "Similarly, in cervical cancer, RBM15 inhibition reduces m6A methylation of OTUB2, leading to the inactivation of the AKT/mTOR pathway, which in turn decreases cell proliferation and metastasis capacity." (PMID 39716068, 2024). "Recent studies have focused on the specific regulatory mechanisms of RBM15 in cervical cancer." (PMID 38915367, 2024). "RBM15 interference in cervical cancer cells could suppress the proliferation, invasion, and migration in vitro and in vivo." (PMID 39582531, 2024). "Furthermore, it has been hypothesized that RBM15 might play a role in promoting the proliferation, invasion, and migration of cervical cancer cells through its interaction with the JAK-STAT pathway." (PMID 38915367, 2024). "In addition, RBM15-mediated m6A modification facilitated the expression of the oncogene Otubain 2 (OTUB2) in cervical cancer cells, which further activated AKT/mTOR signaling, thereby promoting the proliferation, migration, and invasion of cervical cancer cells." (PMID 38915367, 2024). "Specifically, we found lower expression of METTL3, METTL14, and WTAP transcripts, while RBM15 and ALKBH5 abundance was elevated in cervical cancer cells." (PMID 38665783, 2024). "Through further GO and KEGG clustering analysis of the functions of these three factors (YTHDC1, YTHDC2 and RBM15), we infer that ERBB3 methylation plays an important role in the occurrence and progression of cervical cancer." (PMID 35581263, 2022). "The expression of RBM15 and HNRNPA2B1 in our study showed significant differences between cervical cancer and normal samples." (PMID 35572541, 2022). "However, the function of RBM15 in cervical cancer (CC) has not been determined." (PMID 37474926, 2023). "Similarly, in cervical cancer, the HPV E6 protein inhibits autophagy-dependent degradation of RBM15, leading to intracellular protein accumulation without affecting its mRNA levels." (PMID 41403702, 2025).
lung adenocarcinoma (11 papers, 2020 to 2025). A carcinoma that arises from the lung and is characterized by the presence of malignant glandular epithelial cells. "The risk score for each lung adenocarcinoma patient would be calculated with the following formula: risk score = 0.0335 ∗ KIAA1429 + 0.0628 ∗ RBM15 + 0.0106 ∗ HNRNPC." (PMID 33193582, 2020). "RBM15 stabilized XPR1 mRNA through m6A modification to regulate lung adenocarcinoma cell proliferation, invasion, apoptosis, oxidative stress and ferroptosis." (PMID 40682199, 2025). "Among these genes, KIAA1429, HNRNPC, YTHDC2, METTL3, WTAP, YTHDC1, and FTO were down expressed in lung adenocarcinoma, RBM15, ZC3H13, YTHDF1, YTHDF2, and ALKBH5 were up expressed." (PMID 32398949, 2020). "Also, a previous study has verified that RBM15 regulates Ras association domain family 8 (RASSF8) stability via m6A modification to facilitate lung adenocarcinoma progression, which demonstrates RBM15 mediates the m6A modification of other mRNAs." (PMID 40592832, 2025). "RBM15 may have a function as an oncogene in lung adenocarcinoma, according to relevant publications; Su, Huang & Hu (2019) discovered that RBM15 may contribute to the malignant evolution of GC and alter clinical prognosis." (PMID 38436027, 2024). "In addition, a 3-gene risk signature including KIAA1429, RBM15, and HNRNPC was constructed and the lung adenocarcinoma patients in TCGA database were divided into high-risk group and low-risk group based on the median risk score." (PMID 33193582, 2020). "In conclusion, the prognostic signature-based risk score calculated according to the expression levels of KIAA1429, RBM15, and HNRNPC, was not only strongly associated with clinical outcomes and clinicopathological features, but also an independent prognostic factor in lung adenocarcinoma." (PMID 33193582, 2020). "In addition, the prognostic signature-based risk score built according to the expression levels of KIAA1429, RBM15, and HNRNPC, was not only strongly associated with clinical outcomes and clinicopathological features, but also an independent prognostic factor in lung adenocarcinoma." (PMID 33193582, 2020). "In lung adenocarcinoma (LUAD), RBM15 is markedly upregulated and promotes proliferation by stabilizing LDHA mRNA through m6A modification." (PMID 41403702, 2025). "For instance, in lung adenocarcinoma, tumor cells uptake lactate through monocarboxylate transporter 1 (MCT1), which promotes lactylation of RBM15 at the K850 residue." (PMID 41403702, 2025). "Ma MS and colleagues found that RBM15 -mediated m6A modification could stabilize the expression of RASSF8, thereby exacerbating the progression of lung adenocarcinoma cells." (PMID 40830812, 2025).